COL7A1 (collagen type VII alpha 1 chain)
Diseases named in the same sentence as COL7A1 in open-access papers (continued):
Sharing a sentence is not in itself a finding about the gene and the disease.
cancer (continued). "A second possibility is that, because type VII collagen functions as anchoring fibrils between the cancer epithelium and the stroma, increased COL7A1 expression could contribute to cancer cell invasion." (PMID 34512204, 2021). "COL7A1 might be one of the tumor microenvironment components that contributes to cancer progression and distant metastasis." (PMID 34512204, 2021). "In addition, the total score for COL7A1 expression and prevalence of distant metastasis were also significantly higher in cancers with intracellular expression than in those with only extracellular expression." (PMID 34512204, 2021). "Interestingly, preliminary experiments led to the hypothesis that COL7A1 may play a role in cancer progression." (PMID 37345040, 2023). "Eight hub genes (MMP1, MMP7, MMP13, LAMC2, LAMB3, PLAU, COL7A1, and SPP1) were upregulated in both HNSCC and LSCC, suggesting a significant role in cancer progression." (PMID 38707175, 2024). "These genes are key players in cell cycle regulation and cancer, including CDK3 and COL7A1." (PMID 39193365, 2024).
tumor (26 papers, 2015 to 2025). "Deleterious mutations of COL7A1 have been associated with the development of aggressive SCCs in patients suffering from the recessive Hallopeau-Siemens dystrophic epidermolysis syndrome (HS-RDEB) while its restoration delayed tumor cell dissemination in vitro and in vivo." (PMID 26694869, 2015). "This disparity likely stemmed from the fact that a higher COL7A1 expression would provoke a stronger immune response, promoting a greater influx of immune cells and stromal cells into the tumor microenvironment." (PMID 40028167, 2025). "To explore the effect of COL7A1 expression on the immune response of LUAD patients, we investigated the relationship between the COL7A1 expression and the tumor microenvironment in LUAD patients using the ESTIMATE algorithm." (PMID 40028167, 2025). "On the other hand, the Col7a1 gene was two times downregulated in Myd88KO tumor samples compared to WT." (PMID 39000291, 2024). "For example, immunohistochemical studies have demonstrated that COL7A1 is highly expressed in the stroma surrounding tumor cells in solid tumors, such as moderately and poorly differentiated gastric adenocarcinomas, thereby promoting neoplastic processes." (PMID 39769286, 2024). "The only clinical variable that shows better prediction than COL7A1 expression is the tumor stage, especially for stage IV tumors." (PMID 37345040, 2023). "COL7A1 is generally weakly expressed in tumor tissue (for around 70% of the patients), and high expression of this gene is a sign of poor prognosis." (PMID 37345040, 2023). "On the other side, the GSEA analysis showed a strong downregulation in multiple metabolic pathways, with the strongest decrease being mitochondrial oxidative phosphorylation in patients with high tumor expression of COL7A1." (PMID 37345040, 2023). "In the epithelium, COL7A1 was expressed in the cytoplasm, similar to skin cells highly expressing COL7A1, suggesting that these tumor cells are also expressing and secreting high levels of COL7A1." (PMID 35120467, 2022). "When we visualized the gene expression result in a heatmap and magnified the portion in the yellow box, COL7A1 was upregulated in tumor tissue (red) compared with normal tissue (black)." (PMID 34512204, 2021). "In esophageal squamous cell carcinoma, COL7A1 expression correlates with the depth of tumor invasion, lymphatic invasion, and prognosis." (PMID 34512204, 2021). "Further investigations are needed to clarify the complex mechanisms of carcinogenesis and the interaction between COL7A1 and various components of the tumor microenvironment." (PMID 34512204, 2021). "Cases in which the tumor location was the whole stomach were more frequently found in the COL7A1-high group than in the COL7A1-low group (17.5 versus 5.6%, p = 0.046)." (PMID 34512204, 2021). "As COL7A1 was highly expressed in tumor tissues than in normal gastric tissues, we selected the gene as the target gene of our study." (PMID 34512204, 2021). "In CSCCs, tumor cells with COL7A1 knockdown manifested increased migration and higher invasiveness, accompanied by the alteration of EMT marker expression (the decreased expression of E-cadherin and the increased expression of MMP2 and vimentin)." (PMID 29499655, 2018). "Excess expression of both Collagen (COL11A1, COL7A1) and Integrin (ITGA2) is known to be associated with cell invasiveness and tumor formation." (PMID 28821810, 2017). "Moreover, in gastric carcinoma immunohistochemistry, it was observed that expression of type VII collagen alpha chain (COL7A1) was higher in tumor tissue than in healthy tissue, mainly localized in the extracellular matrix." (PMID 39769286, 2024). "When compared to the overall expression of protein-coding genes in tumor samples, COL7A1 appears to be, in general, a weakly expressed gene, with a median expression of 0.8 (0.74–0.856), while the median expression of all protein-coding genes is 3.058 (3.055–3.06)." (PMID 37345040, 2023).
tumor (continued). "Additionally, when comparing the COL7A1 tumor expression across patients with different clinicopathological characteristics, we found that COL7A1 tends to be more expressed in patients of higher stage and grade." (PMID 37345040, 2023). "In addition to improving prediction atop tumor stage, COL7A1 expression was able to improve survival prediction atop tumor grade as well." (PMID 37345040, 2023). "We found that the expression of COL7A1 was negatively correlated with tumor-infiltrating monocytes which obviously may be considered an indicator of the overall survival rates of LUSC patients." (PMID 35993054, 2022). "Furthermore, to confirm the result of this study, we need more validation studies with tissues of good quality to reveal the biological interaction and mechanism between COL7A1 and tumor cells." (PMID 34512204, 2021). "Above all, we also found intracellular expression of COL7A1 in tumor cells." (PMID 34512204, 2021). "Interestingly, COL7A1 expression showed better prediction than tumor grade or the age of patients." (PMID 37345040, 2023). "Therefore, this TIC potentially down-regulated the expression of the COL7A1 and UCN2 genes during and after chimera fusion; and it is thereby associated with poor clinical prognosis because both COL7A1 and UCN2 possessed explicit suppressor roles in tumor EMT regulation." (PMID 29499655, 2018). "The expression of three hub genes, COL7A1, MSLN, and CHRDL1, was significantly correlated with tumor-infiltrating monocytes." (PMID 35993054, 2022). "Col1a1, Col1a2, Col2a1, Col3a1, and Col5a2, which were commonly found in normal ECM of mouse, pig, and human breast tissues, were also identified in tumor ECM in addition to Col4a2, Col5a1, Col6a1, Col6a2, Col6a3, and Col7a1." (PMID 36547361, 2022). "For instance, COL8A1, COL8A2, and COL21A1 were only detected in normal tissues whereas COL7A1 and MUC1 were exclusively identified in tumor samples." (PMID 34199725, 2021). "Three hub genes, COL7A1, MSLN, and CHRDL1, were identified from 513 robust DEGs using a series of bioinformatics methods, which were significantly correlated with tumor-infiltrating monocytes as well as effective indicators of prognostic outcomes for LUSC patients." (PMID 35993054, 2022). "The results indicated that the upregulated hub genes COL7A1 and JUP were negatively correlated with tumor-infiltrating monocytes, while the downregulated hub genes MSLN and CHRDL1 were positively correlated with tumor-infiltrating monocytes, with a p value < 0.05." (PMID 35993054, 2022). "COL7A1 immunohistochemistry scores and site of expression from normal and tumor tissue." (PMID 34512204, 2021). "We could not elucidate the intrinsic genetic and epigenetic mechanism responsible for COL7A1-UCN2 generation; however, both the COL7A1 and UCN2 genes had explicit suppressor roles in tumor regulation, specifically the regulation of the epithelial-mesenchymal transition (EMT)." (PMID 29499655, 2018).
genetic diseases (8 papers, 2015 to 2025). "This ultra-rare and life-threatening genetic disorder stems from mutations in the collagen type VII alpha 1 chain (COL7A1) gene, which encodes collagen VII (COL7)." (PMID 38530400, 2024). "This non-viral gene editing strategy can be further applied for deleting other COL7A1 exons containing mutations, and CRISPR-Cas9-based gene editing therapy for other EB subtypes and other genetic diseases." (PMID 38027067, 2023). "As a monogenic disease gene, COL7A1 constitutes a potential target for antisense oligomer-mediated exon skipping, a therapy applicable to a growing number of other genetic disorders." (PMID 33081018, 2020). "Using a simple screening system, we developed an efficient COL7A1-specific dRTM and demonstrated for the first time endogenous mRNA repair in a genetic disease model." (PMID 27669223, 2016).
genodermatosis (7 papers, 2010 to 2026). "This genodermatosis is a rare autosomal dominant (DDEB [MIM#131750, #131800]) or recessive (RDEB [MIM#226600]) disorder caused by mutations in COL7A1 gene [MIM*120120], encoding type VII collagen (protein component of anchoring fibrils)." (PMID 20920254, 2010).
COL7A1 also shares sentences with these, for which no sentence is quoted: skin disorder (7 papers); infection (4); cutaneous squamous cell carcinoma (2); dyskeratosis congenita (2); junctional epidermolysis bullosa (2); lung adenocarcinoma (2); urothelial carcinoma (2); adrenocortical carcinoma (1); anemia (1); ankyloglossia (1); autosomal recessive congenital ichthyosis (1); basal cell carcinoma (1); bullous dermatosis (1); bullous pemphigoid (1); cervical cancer (1); Chiari malformation type I (1); cholangiocarcinoma (1); colorectal cancer (1); Crohn disease (1); cystic fibrosis (1); endothelial dysfunction (1); epidermolysis bullosa acquisita (1); erectile dysfunction (1); esophageal cancer (1); hematological malignancies (1); Hepatic fibrosis (1); ichthyosis (1); Kennedy disease (1); kidney cancer (1); leukemia (1).
A further 18 diseases each share a sentence with COL7A1 in 1 paper.